TCF7L2 (transcription factor 7 like 2)
Diseases named in the same sentence as TCF7L2 in open-access papers (continued):
Sharing a sentence is not in itself a finding about the gene and the disease.
cancer (continued). "The previous studies have focused on the important role of TCF7L2 in oncogenesis and cancer progression." (PMID 26393635, 2015). "The transcription factor 7-like 2 (TCF7L2) gene has been suggested to play an important role in the pathogenesis of cancer." (PMID 23951231, 2013). "By analysis of the TCF7L2 ChIP-seq datasets from 6 different human cancer cell lines, we identified 116,270 TCF7L2 binding sites, with each cell type having approximately 25,000 to 50,000 TCF7L2 peaks." (PMID 22951069, 2012). "Here, we tested the correlation between mRNA expression of MYC and several alternatively spliced forms of TCF7L2 in 117 non-cancer colon samples." (PMID 19895682, 2009). "While the regulation of TCF7L2 is important for many pathologic outcomes, we wanted to look at it in the context of cancer." (PMID 19924301, 2009). "In addition, cancers with alterations in RNF43, CTNNB1, and TCF7L2 displayed high rates of mutations in receptor tyrosine kinases, MMR-associated genes and DDR-associated genes, independently of the presence or absence of concomitant APC alterations." (PMID 40061138, 2025). "Recent studies have also shown that TCF7L2 can affect the progression of cancer." (PMID 39060928, 2024). "Four genes, RAB10, KLF5, TCF7L2, and CTNNB1 had gene essentiality strongly correlated with both SMAD4 mutation and SMAD4 CNA in various cancer cells (i.e., genes that are more essential when SMAD4 copy number is decreased or when SMAD4 is mutated, P values inferior to 1E-04)." (PMID 37377893, 2023). "While this could indicate that CRC cell lines retain to varying degrees some vestiges of the function of β-CATENIN and TCF7L2 in normal tissue, it could also be that these factors are parts of cancer-specific regulatory circuits controlling cell proliferation." (PMID 36609428, 2023). "This suggested that TCF7L2 exerts a cancer-promoting role in the nucleus of GC cells." (PMID 35864968, 2022). "Furthermore, these cancer pathways were jointly enriched in four genes, TCF7L2, NRAS, CTNNB1, and KRAS, which are mainly involved in cell proliferation." (PMID 36399471, 2022). "The transcription factor 7-like 2 (TCF7L2) gene may affect cancer development and prognosis because the TCF7L2 gene plays an important role in the Wnt/β-catenin signaling pathway." (PMID 34305772, 2021). "TCF7L2 may affect cancer progression and plays a central role in cancer proliferation, migration, and invasion." (PMID 34305772, 2021). "TCF7L2 plays a significant role in the pathogenesis of human cancers." (PMID 34305772, 2021). "Nonetheless, the combined results of the expression analyses in cell lines and tumors suggest that loss of TCF7L2 can suppress a regulatory network that otherwise might mobilize CRC cells and thereby promote cancer cell dissemination." (PMID 32203164, 2020). "This affected 17/333 pathway-associated genes including six known cancer genes (HNRNPA2B1, STAG2, TCF7L2, SUZ12, CLTC, and ZNF521), Thus, the integration procedure prioritized specific pathway-related genes compared to their original rankings in individual mutation datasets." (PMID 32024846, 2020). "These three genes (i.e. FOXO3, NCOA3, and TCF7L2) also play roles in other human cancers." (PMID 29301589, 2018). "In this pathway, TCF4, also called TCF7L2, forms a complex with beta-catenin, and the beta-catenin–TCF4 transcription factor complex binds preferentially to the cancer risk-associated rs6983267 (G) allele in vivo and in vitro leading to a two-fold change in c-MYC expression." (PMID 29232378, 2017).
cancer (continued). "The TCF7L2 rs7903146 C>T, rs290481 T>C, LEP rs7799039 A>G, rs2167270 G>A and LEPR rs1137100 G>A, rs1137101 G>A and rs6588147 G>A polymorphisms were genotyped by SNPscan genotyping assays in 507 ESCC cases and 1,496 non-cancer controls." (PMID 29312594, 2017). "Genes including E-cadherin (Cdh1, up), amphiregulin (Areg, down), c-Met/hepatocyte growth factor receptor (Met, down) and c-Myc (Myc, down) were notable examples of genes involved in cell growth, differentiation and cancer that were significantly regulated by Tcf7l2 silencing." (PMID 25414334, 2014). "Third, although ethnicity plays an important role in the association of TCF7L2 rs7903146 polymorphism with cancer risk, we did not perform the further subgroup analysis by ethnicity because of limited studies for each cancer type." (PMID 23951231, 2013). "Understanding the regulation of TCF7L2 may have implications other than in the context of cancer research." (PMID 19924301, 2009). "Moreover, it would be of interest to investigate how pathogenic or non-pathogenic TCF7L2 mutations affect the sensitivity of cancer cells to TNIK inhibitors." (PMID 40061138, 2025). "In sum, it appears that the mitogenic effects of WNT/β-CATENIN pathway activity found in healthy IECs might be partly retained in HT29, HCT116, and SW480 CRC cells, but the strict dependence on β-CATENIN and TCF7L2 for proliferation and survival appears to be alleviated in the cancer cells." (PMID 36609428, 2023). "It was speculated that TCF7L2 is cancer-promoting in OS with controlling the Wnt/β-catenin pathway." (PMID 34753394, 2022). "In the current study we sought to determine, whether the expression of TCF7L2 splicing forms we identified in non-cancer colon samples correlated with MYC expression and whether this expression was dependent on alleles of rs6983267 or interaction of rs6983267 with TCF7L2 expression." (PMID 19895682, 2009). "In a previous publication, an overexpression of transcription factor TCF7L2 and BCL9 was found, which is known to promote tumor progression by conferring enhanced proliferation, metastatic, and angiogenic properties to cancer cells." (PMID 37285354, 2023). "Results suggested that EphA2-SE recruits TCF7L2 and FOSL2 through the core component E1 to directly target EphA2 and promote tumor progression in cancer cells." (PMID 33712565, 2021). "The genomic region spanning rs6983267 contains DNA enhancer elements that bind to transcription factor 7-like 2 (TCF7L2) and β-Catenin, and induce the production of cancer stem cell (CSCs)." (PMID 34868956, 2021). "Conversely, the expression levels of transcription factors TCF7L1, TCF7L2 and LEF1 in the Wnt/β-catenin signaling pathway were higher in cancer tissue in both homozygous and heterozygous variation types of the patients." (PMID 29050326, 2017). "A chromosomal translocation generating a gene fusion of TCF7L2 and VT11A was seen in 3 % of CRC and also NAV2-TCF7L1 fusion in three cancers." (PMID 27325016, 2016). "The results suggested that TCF7L2 rs7903146 polymorphism might not be associated with cancer risk." (PMID 23951231, 2013). "The WNT pathway is often constitutively activated in cancers, leading to increased levels of nuclear CTNNB1 and up-regulation of TCF7L2 target genes." (PMID 22951069, 2012). "In the cancer pathway cluster, CASP9 and PIK3R1 are both involved in 7 different cancer pathways, while SOS1 and TCF7L2 are both involved in 5 different pathways." (PMID 23281828, 2012).
cancer (continued). "Furthermore, we were able to detect the interactions between SOX9 and TCF7L2 by co‐immunoprecipitation, which is in line with previously reported interactions between SOX9 and other TCF family proteins in other cancer models." (PMID 39492805, 2024). "Our results revealed that SOX9‐TCF7L2 double‐high cancer cells exhibited significantly higher level of P21 compared to SOX9‐TCF7L2 double‐low cells, supporting a P21‐mediated G1/S cell cycle arrest in SOX9/TCF7L2 double‐high GBC cells." (PMID 39492805, 2024). "Moreover, pan‐cancer expression analysis of the TCGA and CCLE datasets revealed that GBC ranked among the top cancer types in terms of SOX9 and TCF7L2 mRNA levels." (PMID 39492805, 2024). "Altogether, it thus appears that certain aspects of the function of TCF7L2 in healthy IECs might be conserved in CRC cells, but the strict addiction to β-CATENIN/TCF7L2-driven transcription could be lost during cancer progression." (PMID 36609428, 2023). "In addition, these four cancer pathways were jointly enriched in four genes, CTNNB1, TCF7L2, NRAS, and KRAS, mainly involved in cell proliferation." (PMID 36399471, 2022). "Of the top 20 genes in TCGA or MSKCC, AMER1, SOX9, ARID1A and TCF7L2 were not included in our cancer panel." (PMID 34074070, 2021). "Finally, miR-486-5p also promote the expression of five genes with promoting cancer roles: KDM4C, PPARD, KLF4, STAT3, and TCF7l2." (PMID 33227890, 2020). "Here, we prove the feasibility of assigning genes to cancer pathways by genome-wide forward genetics using genome-edited human cell systems, link FOXO3, NCOA3, and TCF7L2 to phenotypes of the EGFR/Ras/MAPK pathway, and implicate FOXO3 and NCOA3 in the response to anti-EGFR therapy." (PMID 29301589, 2018). "Additionally, the lncRNA colon cancer-associated transcript 2 (CCAT2) enhances WNT activity by binding to TCF7L2, a pivotal transcription factor in the WNT signalling pathway, and facilitates MYC activity, thereby enhancing cancer cell invasion and metastasis." (PMID 29137343, 2017). "We found that the expression levels of the genes in the Wnt/β-catenin signaling pathway, including APC, β-catenin, TCF7L1, TCF7L2, LEF1, MMP7, C-myc, C-jun, CYCLIND1 and GSK-3β, were remarkably higher in cancer than non-cancer tissues in the p.1125Val>Ala mutant FAP family members." (PMID 29050326, 2017). "In many cancer cells, TCF4/TCF7L2 is localized to the nucleus." (PMID 28536608, 2016). "Although there were data available for ChIP-seq of androgen receptor (AR), FOXA1 and NKX3-1, data for TCF7L2— another transcription factor with a proposed role in prostate- and other cancers — was not available." (PMID 24497837, 2014). "The fusion transcripts were both seen in 29% of the normal colonic mucosa samples, and in 25% and 75% of the tested normal tissues from other organs, revealing that the TCF7L2 fusion transcripts are neither specific to cancer nor to the colon and rectum." (PMID 24608966, 2014). "TCF7L2 has a key role in the Wnt/beta Catenin signaling that is known to have an important function in the induction of HCV-related HCC and represents a critical process for the invasiveness and metastatic development of several human cancers." (PMID 24658135, 2014). "PIK3CA-mutant cancers displayed higher expression of 12 of the 17 Wnt genes compared to PIK3CA wild-type tumors, including five Wnt target genes (LEF1, MYCN, FZD7, SFRP2, and TNFRSF11B) and seven Wnt signaling components (TCF7L1, TCF7L2, CTNNB1, FZD4, SFRP1, WNT5A, and MSX2)." (PMID 34035258, 2021). "Some factors identified (e.g., NF-κB, STAT3, FOS) are known to be involved for transformation in our model, others (e.g., CEBPB, HIF1a, ETS2, FHL2, TCF7L2, and NFE2L2) have been described as oncogenes in other settings, and some proteins (BHLHE40 and MAFB) have not been well linked to cancer." (PMID 29802342, 2018). "However, the combinatorial epigenetic profile of TCF7L2 in these cancer types has not been well studied." (PMID 28499350, 2017).
cancer (continued). "However, because few reports have described the mechanisms mediating Wnt signaling activation in ESCC, the factors that regulate TCF4/TCF7L2 expression in this type of cancer are not known." (PMID 28536608, 2016). "The observation that TCF7L2 involving fusion transcripts are detectable in such a large fraction of CRC samples, but also normal colonic mucosa and other normal tissue types, reveals that the TCF7L2 fusion transcripts are neither specific to cancer nor to the colon and rectum." (PMID 24608966, 2014). "Therefore, to ensure that the cell type specificity that we observed was not due to TCF7L2 peaks in amplified regions, we used our peak-calling program Sole-search to identify all genomic amplifications in the six cancer cell lines." (PMID 22951069, 2012). "As a consequence, we rule out that cancer-specific neoexpression and compensation by other TCF/LEF family members account for expendability of TCF7L2 and suggest that this much more likely reflects far-reaching WNT/β-CATENIN pathway independence of CRC cell lines." (PMID 36609428, 2023). "Moreover, CCAT2 was shown to promote cancer growth, metastasis, and induce chromosomal instability, and CCAT2 upregulated MYC expression through the activation of the Wnt signaling pathway by promoting TCF7L2 transcriptional activity rather than by increasing the quantity of TCF7L2." (PMID 26307974, 2015).
tumor (101 papers, 2010 to 2026). "This was confirmed, enabling us to use this mouse line to inactivate Tcf7l2 in tumor cells and study the effects of Tcf4 loss on their development." (PMID 40221753, 2025). "Integration of GWAS and RNA-seq revealed that 24 CRC-associated genes, including PYGL, SMAD7, and TCF7L2, are involved in tumor metabolism and Wnt/TCF signaling." (PMID 41144378, 2025). "Using conditional alleles of Tcf7l2 and Apc in combination with Defa6-iCre, we were able to analyze the effects of Tcf4 loss on a subpopulation of cells within the developing tumor." (PMID 40221753, 2025). "The results showed that the number of tumour loops associated with TCF7L2 was greater than that associated with normal tissue, and the expression level was up‐regulated in tumour tissue." (PMID 38769659, 2024). "It was affirmed that miR-22-3p was associated with distant metastasis and tumor size in OS patients, and reduced in OS tissues and cells while transcription factor 7-like 2 (TCF7L2) was elevated." (PMID 34753394, 2022). "Of the 10 most significantly mutated genes in CRLM, TCF7L2 showed a significantly higher alteration frequency in right side (29.2%) than in left side (9.2%) tumours (p = 0.013)." (PMID 35860598, 2021). "How is the diminished proliferation in the Tcf7l2-deficient epithelium related to the possible tumor-suppressive role of the factor?" (PMID 27447672, 2016). "After correction for multiple testing, 26 shared factors were highlighted in both analyses: for example, tumor status was associated with decreased methylation at binding sites of TCF7L2 and EZH2, likely reflecting methylation changes characteristic for CRC genesis in general." (PMID 40102611, 2025). "In addition, we further elucidated that only the TCF7L2 variant containing exon 13 promoted ccRCC cell proliferation and tumor growth." (PMID 39865075, 2025). "Notably, anoikis resistance is a key pre-step for distant tumor metastasis, and TCF7L2 was closely associated with the anoikis resistance of GC cells." (PMID 35864968, 2022). "ERBB2, CEBPA and TCF7L2 mutated tumors tend to have higher tumor mutation burden (TMB)." (PMID 34970478, 2021). "The loss of TCF7L2 enhances tumor cell growth, whereas a gain inhibits tumor cell growth." (PMID 34305772, 2021). "This view contrasts with the frequent occurrence of TCF7L2 loss-of-function mutations in CRC genomes, arguing that TCF7L2 activity may rather be tumor-suppressive." (PMID 32203164, 2020). "Nonetheless, the observation of frequently occurring TCF7L2 loss-of-function mutations in human CRC genomes likewise pointed to potential tumor suppressor properties of TCF7L25,13,14, and indicated that CRC cells unlike healthy IECs may not depend on TCF7L2 to stay alive." (PMID 36609428, 2023). "YY1 recruits BETs (including BRD2, BRD4) to bind to cis-regulatory elements of transcription factor 7 like 2 (TCF7L2), thereby regulating the expression of TCF7L2, cooperatively activating tumor cell DNA repair capacity and driving therapeutic resistance." (PMID 40867514, 2025). "We observed that when TAD gained and loops were increased in TCF7L2 gene area, its expression was up‐regulated in tumour." (PMID 38769659, 2024). "In our literature review, we found that genes such as SRSF3, TCF7L2, FOXP1, and CEP55 have been documented to be associated with epithelial-mesenchymal transition (EMT) in tumor cells." (PMID 38254188, 2024). "Taken together, SOX9 and TCF7L2 formed a transcriptional co‐dependent circuit and were indispensable for maintaining tumor malignancy of GBC in vitro and in vivo." (PMID 39492805, 2024). "In the TCF7L2 gene area, we observed TADs gained and loops increased, along with an upregulation of its expression in the tumour, which potentially promotes tumour cell proliferation and GH secretion." (PMID 38769659, 2024).